Y_RNA (Y RNA )
Gene: Miscellaneous RNA gene on chromosome 12 (32,396,050 to 32,396,147, reverse strand). Ensembl gene ENSG00000207176.
Homologues: Orthologues: chimpanzee Y_RNA (99% identical). Paralogues in human: RNY3P14 (87% identical), Y_RNA (87% identical), Y_RNA (86% identical), RNY3 (85% identical), Y_RNA (85% identical), RNY3P1 (84% identical), Y_RNA (84% identical), Y_RNA (83% identical), Y_RNA (82% identical), RNY3P11 (81% identical), Y_RNA (81% identical), RNY3P2 (80% identical), and 91 more.